PIK3R1 (phosphoinositide-3-kinase regulatory subunit 1)
Diseases named in the same sentence as PIK3R1 in open-access papers (continued):
Sharing a sentence is not in itself a finding about the gene and the disease.
Insulin resistance (continued). "Our results support these findings, identifying PIK3R1 as a key target gene, underscoring its integrative role in insulin resistance and abnormal immune response pathways, connecting AD and T2DM." (PMID 40823947, 2025). "The intersected genes between DEG- and DMR-targeted genes were gathered in type II diabetes mellitus, insulin resistance, and metabolic pathways, which referred to Nos3, Pik3r1, Socs1, and Acly." (PMID 37287451, 2023). "A total of 92 genes were intersected between DEGs and DMRs-targeted genes, of which Nos3, Pik3r1, Socs1, and Acly were gathered in type II diabetes mellitus, insulin resistance, and metabolic pathways." (PMID 37287451, 2023). "This study raised a presumption of the presence of ccr-miR-29a targeting pik3r1 or ccr-miR-143 targeting pik3r3 playing likely roles in Momordica charantia saponins remitting the liver insulin resistance." (PMID 37091861, 2023). "Global or hepatic insufficiency of miR-29 potently prevents the onset of diet-induced insulin resistance by negatively regulating insulin signaling via PIK3R1 regulation, suggesting that miR-29 is an important regulatory factor in metabolism homeostasis." (PMID 33195407, 2020). "Males displayed insulin resistance, through slower glucose clearance despite normal circulating insulin and lower mRNA expression of PIK3R1 and PIK3CB in gonadal fat and liver respectively." (PMID 31300679, 2019). "The current data mining predictive analysis with experimental validation provides the first indication that vitamin D can prevent antipsychotic-induced hyperglycaemia by suppressing insulin resistance via upregulation of Pik3r1." (PMID 27199286, 2016). "PIK3R1, PIK3R2, and PIK3CA, encoding the p110α catalytic subunit, were next sequenced in 262 further probands with severe insulin resistance." (PMID 27766312, 2016). "These experimental data indicate that vitamin D counteracts quetiapine-induced insulin resistance by blocking Pik3r1 downregulation, validating the prediction obtained from analysis of the GEO and KEGG PATHWAY databases." (PMID 27199286, 2016). "Further investigation is required to determine to what extent the expression of Pik3r1 and insulin resistance are affected by a long-term treatment with quetiapine and/or vitamin D." (PMID 27199286, 2016). "Notably, this study revealed that reduced PIK3R1 expression can ameliorate insulin resistance and adipose tissue macrophage accumulation in obese mice." (PMID 41032481, 2025). "SHORT syndrome features short stature and insulin resistance consistent with impaired ligand-induced p110α action, a phenotype distinct from the enhanced insulin sensitivity produced by genetic ablation of one or more Pik3r1 products in mice." (PMID 38077044, 2024). "The mutations of PIK3R1, encoding the p85α regulatory subunit of PI3K, including the most frequent mutation Arg649Trp and 11 other PIK3R1 mutations have been recognized in patients with SHORT syndrome and genetic insulin resistance." (PMID 37664840, 2023). "Reducing Pik3r1 expression also significantly compromises the ability of Dex to inhibit AKT and p70S6 kinase activity and reduces glucocorticoid induction of IRS-1 phosphorylation at Ser307, which is associated with insulin resistance." (PMID 37628845, 2023). "Instead, the underlying mechanism on Momordica charantia saponins ameliorating the liver insulin resistance of common carp might be to conduct the inhibition of ccr-miR-29a targeting pik3r1 or ccr-miR-143 targeting pik3r3." (PMID 37091861, 2023). "Slience of Pik3r1 surppresses insulin resistance in diet-induced obesity (DIO) mice." (PMID 34899339, 2021). "In our study, the patients both presented insulin resistance and lipodystrophy with mutations in the PIK3R1 gene (c.1615‐1617del, c.1945C>T) but without Rieger anomaly." (PMID 32602265, 2020). "We selected the PIK3R1 gene for an in-depth analysis since it is critical for obesity, insulin resistance, and may also be affected by DNA methylation." (PMID 32599690, 2020).
Insulin resistance (continued). "In such circumstances, further inhibition of PIK3R1 could have worsened insulin resistance in the setting of metformin treatment." (PMID 31583022, 2019). "C-terminal mutations in human PIK3R1 are associated with severe insulin resistance in the absence of dyslipidemia or hepatic steatosis." (PMID 27766312, 2016). "For example, Pik3r1, which is involved in insulin resistance and AD, is found in the mouse, Drosophila and C. elegans networks, suggesting that it could be an important conserved modulator of longevity." (PMID 26694192, 2015). "When PIK3R1 is mutated or defective, it may lead to insulin resistance and metabolic abnormalities independent of obesity and dyslipidemia, due to increased energy expenditure." (PMID 40747301, 2025). "SHORT syndrome is an autosomal dominant condition associated severe insulin resistance (IR) and lipoatrophy due to post-receptor defect in insulin signaling involving phosphoinositide-3-kinase regulatory subunit 1 (PIK3R1), where no clear treatment guidelines are available." (PMID 31583022, 2019). "Reduced expression of insulin signalling pathway genes in patients with insulin resistance (INSR, AKT, PIK3R1, IRS2) indicates a diminished insulin response in both VAT and SAT." (PMID 40806527, 2025). "Several studies in transgenic mouse models have shown that the inhibition of Pik3r1 enhances PI3K activity and improves insulin signaling and glucose homeostasis in high fat diet fed obese mice and mice with genetically induced insulin resistance." (PMID 36287121, 2022). "Thus, PIK3R1 C-terminal mutations impair insulin signaling only in some cellular contexts and produce a subphenotype of insulin resistance resembling INSR dysfunction but unlike AKT2 dysfunction, implicating PI3K in the pathogenesis of key components of the metabolic syndrome." (PMID 27766312, 2016). "Notably, IL6, NFKBIA, NFKB1, NOS3, PTPN1, PIK3R1, and STAT3 (members in the enriched WGCNA module) have been shown to alter insulin resistance." (PMID 33005175, 2020). "C-terminal PIK3R1 mutations cause SHORT syndrome, as well as lipodystrophy and insulin resistance (IR), surprisingly without fatty liver or metabolic dyslipidaemia." (PMID 32439336, 2020). "Specifically, there were quantitative differences between the expressions of IRS1, PIK3R1, SLC2A1, SLC2A3, and SLC2A4 among the patients with GDM during pregnancy and at 1-year postpartum, i.e., in the two studied groups differing in the degree of insulin resistance." (PMID 39684804, 2024). "Therefore, we speculated that vitamin D lessens quetiapine-induced hyperglycaemia by inhibiting the downregulation of Pik3r1/PI3K and subsequent induction of insulin resistance." (PMID 27199286, 2016).
endometrial cancer (44 papers, 2012 to 2025). Primary or metastatic malignant neoplasm involving the endometrium (mucous membrane that lines the endometrial cavity). "Tolerable safety profile; partial response in endometrial cancer with PIK3R1/PTEN mutations; RP2D is 200 mg twice daily." (PMID 40740483, 2025). "Somatic mutations in the PIK3R1 gene have been reported in 4.4% of all tumors, with the highest frequency in endometrial carcinoma (31%), glioblastoma multiforme (11%), and colorectal cancer (8%)." (PMID 39858051, 2025). "Second, by searching the literature, we found VEGFA and PIK3R1 protein are the most interconnected among our selected cancer type risk factors, including Endometrial cancer, Ovarian cancer, Cervical cancer and Thyroid cancer." (PMID 36608061, 2023). "Of the genes involved in this pathway examined in our study, PTEN, PIK3CA, and PIK3R1 all mutated frequently, which was similar to the TCGA study on endometrial carcinoma." (PMID 30886832, 2019). "A handful of studies showed that polymorphisms of PIK3R1 were associated with survival in bladder cancer and endometrial cancer." (PMID 28280736, 2017). "One patient’s tumor was determined to harbor a PIK3R1-K567E mutation, which has been observed in endometrial cancer." (PMID 24326041, 2013). "The discovery of novel variants in BRIP1, MLH1, and PIK3R1 further challenges the current understanding and suggests that endometrial cancer may involve a broader array of genetic alterations than previously recognized." (PMID 39296440, 2024). "In our cohort, breast and endometrial cancers each harbored 40% of the PIK3R1 mutations." (PMID 36934165, 2023). "We therefore searched our in-house endometrial cancer data set and The Cancer Genome Atlas (TCGA) for cancer patient-derived PIK3R1 mutations that could target p85α homodimerization." (PMID 26222500, 2015). "However, PIK3R1 mutations outside the nSH2-iSH2-cSH2 fragment are relatively common in cancers, particularly endometrial cancer." (PMID 26222500, 2015). "The molecular characteristics of endometrial carcinomas revealed distinctive PTEN, PIK3CA, PIK3R1 and K-RAS mutation." (PMID 41233892, 2025). "Among the members in a phosphatidylinositol 3-kinase (PI3K) pathway, mutations of PIK3R1 disrupt the genome stabilizing roles of PTEN, potentially synergizing PTEN losses in endometrial cancers." (PMID 39160568, 2024). "Established evidence proves that co-mutations in PIK3R1 and PIK3R2, the members of PI3K-Akt signaling pathway, are mainly involved in the development of endometrial cancer." (PMID 35893039, 2022). "Gene mutations in PIK3CA, PIK3R1, KRAS, PTEN, and PPP2R1A commonly detected in type I endometrial cancer lead to PI3K/Akt/mTOR pathway activation." (PMID 34831139, 2021). "In breast and ovarian cancer patients, the inhibition of the PI3K/AKT/MTOR pathway with PIK3R1 inhibitors (temsirolimus, ridaforolimus, everolimus) have been shown to satisfactory clinical outcomes of patients with endometrial cancer in Phase II trials." (PMID 34367229, 2021). "Gene mutations in PIK3CA, PIK3R1, KRAS, PTEN, and PPP2R1A commonly detected in type I endometrial cancer cause high activation of the PI3K/Akt/mTOR pathway." (PMID 34831139, 2021). "A total of 49 FFPE and LBC specimens (n = 24) were analyzed, revealing characteristic mutations for endometrial cancer, including PTEN, CTNNB1, PIK3CA, and PIK3R1 mutations." (PMID 32652986, 2020). "These endometrial cancers showed common mutation profiles, including PTEN, CTNNB1, PIK3CA, and PIK3R1 mutations." (PMID 32652986, 2020).
endometrial cancer (continued). "While colon cancers, endometrial cancers, and GBM's have been shown to contain a high frequency of PIK3R1 mutations, sequencing of more than 200 non-small cell lung cancer tumors did not identify mutations in PIK3R1." (PMID 23166678, 2012). "PIK3R1 mutations have been reported in several types of cancer, including endometrioid endometrial cancers, non-endometrioid endometrial cancers, glioblastomas, breast, ovarian, and colon tumors." (PMID 37569808, 2023). "According to several studies, miR-495 reduces inflammatory events by inhibiting the inflammasome signaling pathway and may act as a tumor suppressor by directly targeting PIK3R1 gene in endometrial cancer cells." (PMID 34399692, 2021). "Mutations in PIK3CA, PIK3R1, and KRAS also occur at high frequency in endometrial carcinoma." (PMID 34831139, 2021). "Other interesting findings from the NGTS were: (i) frequent detection of RNF43 mutations in both dVIN and de-VIL, which have been previously associated with endometrial carcinoma, and (ii) detection of mutations in KEAP1, CDH1, PIK3R1, and POLE exclusively in de-VIL." (PMID 33918187, 2021). "Furthermore, PIK3R1 was overexpressed in endometrial cancer cells, and upregulation of miR-495 impeded endometrial cancer cells proliferation while induced apoptosis by directly targeting PIK3R1." (PMID 32817745, 2020). "PIK3R1 represents a critical driver of endometrial cancer pathogenesis and is a therapeutic target." (PMID 32293263, 2020). "For example, in endometrial cancer (EC), miR-495 was downregulated in tumor tissues, and overexpression of miR-495 markedly inhibited tumor cell proliferation and promoted cell apoptosis via targeting PIK3R1." (PMID 31771650, 2019). "The identification of novel variants in genes such as ARID1A, BRIP1, MLH1, PIK3R1, and PTEN expands the understanding of the genetic basis of endometrial cancer, suggesting that a broader spectrum of mutations may contribute to the disease than previously recognized." (PMID 39296440, 2024). "The detection of specific mutations in genes such as PTEN, PIK3R1, CTCF, and BRAF, which correlate with advanced disease features like high-grade tumors and deep myometrial infiltration, suggests that cfDNA analysis could become a crucial tool in the clinical management of endometrial cancer." (PMID 40227624, 2025). "These are ERRFI1, IL6, PIK3R1 and SPRY2 which were found to be upregulated and YWHAZ which was found to be downregulated; Endometrial cancer has twelve genes." (PMID 34764329, 2021). "PTEN, PIK3R1, and ARID1A alterations were significantly more commonly occurred in cases of endometrial cancer than in EIN (p all < 0.05)." (PMID 30886832, 2019). "Further, we examined The Cancer Genome Atlas (TCGA) for endometrial cancer and found genetic alterations in 95% (229/242) of patients in several key components of the PI3K-mTOR pathway, including PI3KCA (57%), PTEN (67%), PIK3R1 (33%) and mTOR (12%)." (PMID 27980219, 2017). "PIK3R1 mRNA expression is also markedly lower in tumors than in normal tissues across multiple cancer types, including breast, lung, kidney, prostate, and endometrial carcinomas." (PMID 39858051, 2025).
glioblastoma (43 papers, 2010 to 2025). The most malignant astrocytic tumor (WHO grade IV). "Another study found that PIK3R1 mutation was associated with poor prognosis in the mesenchymal subtype of glioblastoma." (PMID 40564017, 2025). "PIK3R1 mutation rates vary within the context of glioblastoma, but according to the Cancer Genome Atlas, the mutation frequency of PIK3R1 in glioma is 9.9%." (PMID 40564017, 2025). "Research has found a connection between specific glioblastoma subtypes and PIK3R1 mutations, with most observed in the mesenchymal subtype." (PMID 40564017, 2025). "Activating mutations in PIK3R1 have been reported in several cancers, including colon cancer and glioblastoma, and lead to the activation of the PI3K-AKT pathway." (PMID 36810562, 2023). "PIK3R1 and Notch1 mutations have been previously identified in patients with glioblastoma and low‐grade astrocytoma, correlating with shorter overall survival." (PMID 37667984, 2023). "The mutation of PIK3R1 has been found in colorectal, breast, and ovarian cancer, and is also a potential therapeutic target in glioblastoma multiforme, as it regulates tumor cell growth and motility." (PMID 34367229, 2021). "Recently, recurrent somatic mutations in PIK3CA and PIK3R1 were identified in 6–15 and 10% of glioblastomas, respectively, which were accompanied by activated PI3K signaling." (PMID 31036078, 2019). "PIK3R1 mutations have been shown to occur at high frequency (25%) in endometrial cancer and at lower frequencies in several other cancers, including glioblastomas (7–10%22,38), colorectal cancers (8%23) and bladder cancer (6%25)." (PMID 29740032, 2018). "With respect to glioblastoma, PIK3R1 mutations represent one of the most common genetic aberrations, and the phosphoinositide 3-kinase (PI3K) pathway is one of the most frequently targeted signaling pathways for therapeutic strategies." (PMID 28785028, 2017). "PIK3R1 mutations are less common, although recently it was shown that PIK3R1 was mutated in up to 10% of glioblastomas." (PMID 20407443, 2010). "Similarly, recurring mutations of PIK3R1 gene coding, in detail for the p85 regulatory subunit, have also been detected in endometrial, glioblastoma, uterine carcinosarcoma, and bladder urothelial carcinoma." (PMID 34439105, 2021). "The higher glioblastoma hazards associated with higher levels of Pik3r1 observed in this study are supported by previous work showing that over-expression of this gene plays a role in the activation of the PI3K/Akt pathway resulting in cell proliferation and tumor invasion." (PMID 21649900, 2011). "Pik3r1 and E2f3 were associated with all three glioblastoma survival variables." (PMID 21649900, 2011). "Mutations of PIK3CA, the gene encoding the p110α subunit of PI3K, or mutations of PIK3R1, the gene encoding the p85 regulatory subunit of PI3K, have been demonstrated in approximately 15% of patients with glioblastoma." (PMID 35022057, 2022). "In the present study, we identified novel mutations in a glioblastoma patient and first screened a chemical library of more than 1500 FDA-approved drugs to find established drugs, which target novel BRAF and PIK3R1 mutations." (PMID 33313992, 2021). "PIK3R1 (phosphoinositide-3-kinase regulatory subunit 1) is a potential therapeutic target in glioblastoma multiforme and that it also influences tumor cell growth and motility." (PMID 32047813, 2020). "Activation of the PI3K pathway, which comprises PIK3R1, is evident in many cancers, including glioblastoma." (PMID 28785028, 2017).